ITGB1 (integrin subunit beta 1)
Diseases named in the same sentence as ITGB1 in open-access papers (continued):
Sharing a sentence is not in itself a finding about the gene and the disease.
tumor (continued). "Moreover, the prognostic signature based on ITGB1, ITGB4, ITGB5 and ITGB6 may facilitate clinicians to identify more aggressive and immunosuppressive tumours and make more individually appropriate therapeutic decisions." (PMID 33073486, 2020). "Some of these proteins are key components of cell-cell or cell-matrix adhesion and includes annexin and integrins such as ANXA1, ANAX2, ITGB1, ITGA3, FN1, CTNNB1, APOH which interplay may activate exosome and leukocyte adhesion to tumor cells to limit tumor growth." (PMID 30111323, 2018). "Treatment effects were determined by assessment of tumor growth, proliferation (Ki67-staining), angiogenesis (CD31-staining), metastasis (immunostaining), EMT markers (western blot), stromal components collagen type I, Itgb1 and FSP1 (immunostaining) and chemotherapeutic efficacy (5FU)." (PMID 28832662, 2017). "In addition, SHARPIN is a negative regulator of integrin beta 1 (ITGB1), a component of cell adhesion and cell recognition in a variety of processes including embryogenesis, hemostasis, tissue repair, immune response, and tumor metastasis." (PMID 24465642, 2014). "Furthermore, six tumor progression genes (GNAI2, ODC1, APP, TNFRSF12A, BASP1, and LARP6) and nine migration and metastasis‐related genes (MSN, FLOT1, LAMB3, MYL9, ITGB1, FTH1, TPM4, and PMEPA1), which could explain the invasive characteristics of SCC, were identified." (PMID 40776410, 2025). "However, in patients with high PPP2CA expression, neither ITGA5 nor ITGB1 exhibited a significant association with overall survival, suggesting that PPP2CA may play a regulatory role in integrin-mediated tumor progression." (PMID 40770810, 2025). "However, they may also promote tumor progression through GAS6-AXL and ANXA1-FPR1 signaling, interacting with fibroblasts, endothelial cells, and monocytes, while the role of MDK-SDC2 and MDK-(ITGA4+ITGB1) signals remains to be elucidated." (PMID 39776914, 2024). "LGALS3 regulated by SOX8/JUN complex was secreted by GSC into the tumour microenvironment, which could not only promote GBM MES transition by binding membrane protein ITGB1 on GSC in an autocrine form, but also promote immunosuppression by binding ITGB1 on TAM in a paracrine manner." (PMID 39629136, 2024). "However, the relationship between ITGB1 and the tumor microenvironment has not been evaluated." (PMID 35864742, 2023). "We also found that Cancer Cells interact with ITGB1 expressed in Fibroblasts, Endothelial Cells, SLC16A7 + Cells, FOXN4 + Cells, Basal Cells, GMP Cells, Monocytes, and NKT Cells through angiogenic signal molecules (VEGFA), which may stimulate tumor growth and metastasis." (PMID 36401283, 2022). "Indeed, the tumor cores (L and LB) were found to express numerous pEMT genes at significantly greater levels than the TME, including the laminins (LAMC1, LAMC2, LAMA3), integrins (ITGA2, ITGB1, ITGAV), and inflammatory and neutrophil-attracting chemokines (CXCL8, CXCL1)." (PMID 36216799, 2022). "Furthermore, tumor cells seeded in a low concentration of collagen gels acquired TIC-like phenotypes and revealed enhanced resistance to chemotherapeutic agents, which was dependent on an integrin β1 (ITGB1)/Y-box Binding Protein 1 (YBX1)/Secreted Phosphoprotein 1 (SPP1)/NF-κB signaling pathway." (PMID 34758833, 2021). "In addition, tumor cells exhibited elevated ITGA5 and VIM levels and reduced integrin β1 (ITGB1) and CDH1 levels after suspended coculture with CAFs in MUs, thus indicating that interaction with CAFs in MUs could further maintain the ITGA5high mesenchymal phenotype in ATCs." (PMID 30710055, 2019). "The rPSL-DIA and biological-rPSL-DIA demonstrated trends similar to biological-library-DIA and library-free DIA, significantly differentiating between noncancerous and tumour tissues for proteins such as S100A8 and ITGB1." (PMID 40348885, 2025).
tumor (continued). "Interestingly, CFPAC-1 endocytosis of ITGB1 was not affected by AP2M1 depletion or Pitstop2 treatment, validating the results of the plasma membrane proteomics and suggesting that integrin endocytosis is independent of clathrin in cell lines where AP2 loss did not enhance tumor growth." (PMID 40050266, 2025). "Treating tumor‐bearing mice with DNase I, to degrade NETs‐DNA, specifically blocked ITGB4 but not ITGB1‐driven metastatic colonization." (PMID 37828611, 2023). "In the tumor stroma, the mRNA levels of Integrin β1 are not changed following TAC and are significantly lower in the tumors derived from both ITGB1 KO and Renca cancer cells." (PMID 38139195, 2023). "No change in stromal Itgb1 and FSP1 was found in either tumor model." (PMID 28832662, 2017). "While ITGB1 and CD47 may not show strong differential expression between tumor and adjacent tissues, their functional role in tumor invasion, immune evasion, and metastatic competence has been repeatedly demonstrated, supporting them as functional rather than diagnostic targets." (PMID 41596257, 2026). "Consequently, we believe that due to different tumor microenvironments and active signaling pathways occurring in these distinct systems, SLUG may not be part of the same pathway as ITGB1 in CTCs of hepatic or prostate origin." (PMID 32630254, 2020).
cancer (298 papers, 2008 to 2026). A tumor composed of atypical neoplastic, often pleomorphic cells that invade other tissues. "Further analysis of ligand-receptor pairs revealed that VTN-(ITGAV + ITGB5), SEMA4D-PLXNB2, GAS6-TYRO3, and FN1-(ITGA3 + ITGB1) were more prevalent in high-risk cancer cells." (PMID 41034991, 2025). "Lastly, we discussed the effects of ITGB1 on many characteristics of cancer cells and its potential utility as a diagnostic biomarker and a therapeutic target for additional translational research." (PMID 38279122, 2024). "We used four algorithms (EPIC, MCPCOUNTER, XCELL, TIDE) to investigate the correlation between ITGB1 and cancer-associated fibroblasts." (PMID 38402311, 2024). "The findings of the analysis revealed that in 15 cancer species, ITGB1 expression was substantially linked with an immune score, a matrix score, and an ESTIMATE score." (PMID 38402311, 2024). "Complete suppression of carcinogenesis was seen in mice that lack ITGB1 activity, in the mammary gland, tissue-specific loss of ITGB1 function can suppress the development and proliferation of CD24hiCD29loCD61hi cancer cells." (PMID 38279122, 2024). "Loss of expression of either Kindlin-2, TβRI or ITGB1 also inhibited the colony formation potential, a hallmark of cancer cells phenotype, of both MDA-MB-231 and 4T1 cells." (PMID 39300257, 2024). "Combined with the top knowledge analysis results, we have a tendency to conclude that desoxyribonucleic acid copy variety amplification and methylation area unit 2 potential causes of ITGB1 upregulation in cancer." (PMID 38402311, 2024). "KDM5C also bound to the promoters of genes that encode extracellular matrix proteins such as ITGB1 and ITGB1-DT, which have been implicated in cancer progression." (PMID 38383780, 2024). "The most prominent adhesion related cancer targets, whose inhibition caused cytotoxicity and radiosensitization, were integrin β1 (ITGB1), Focal adhesion kinase (FAK; PTK2) and Particular Interesting New Cysteine-Histidine rich protein (PINCH1; LIMS1)." (PMID 37206618, 2023). "In our model, ITGB4 gene (encoding β4) was significantly downregulated in dormant cancer cells in vivo, while ITGB1 (encoding β1) expression remained unaltered." (PMID 37456245, 2023). "In contrast, patients in the high-risk group were enriched in expression genes of cancer-promoting inflammation such as ITGB1 and CD46." (PMID 35832540, 2022). "The acquired TIC-like phenotypes of cancer cells were associated with the activation of ITGB1/YBX1/SPP1/NF-κB signaling." (PMID 34758833, 2021). "Noteworthy, ITGB1 directly participated in modulating mitotic cell cycle pathway, whose aberration has been defined as a hallmark of cancer." (PMID 34977001, 2021). "Moreover, loss of ITGB1 protein expression in actively adhering migratory cancer cells promotes IGF-1R retention at the plasma membrane, impairing its internalization and intracellular trafficking." (PMID 39608716, 2024). "Using scRNA-seq data, we investigated the expression of genes involved in stromal-like signature (FAP, VIM, and ITGB1); cancer-associated fibroblasts (CAFs; POSTN and ACTA2); as well as COL1A1, SULF1, TCF21, and DLK1, which were previously associated with FAP-high or FAP-low CAF phenotypes in OC." (PMID 39634630, 2024). "Consistently, the integrin family was implicated as an important inducer of tumorigenesis, and it was significantly implicated in cancer metastasis, drug resistance, and immune evasion, and it was clear that ITGB1 was one of the most important integrin family members." (PMID 37007126, 2023). "Therefore, we have generated PyMT cancer cells with a loss of function mutation in the Integrin β1 gene (PyMT ITGB1 KO)." (PMID 38139195, 2023). "Hence, ITGA5/ITGB1 internalization may result in cancer cell random scattering due to anisotropic loss." (PMID 38892190, 2024). "Besides, ITGA5 and ITGB1 were risk factors for multiple cancer types." (PMID 36937870, 2023).
cancer (continued). "Through this study, we have identified characteristics of TME in patients experiencing recurrence after CCRT treatment, showing heightened interaction between SPP1‐positive macrophages and cancer cells via CD44 or ITGB1." (PMID 41466485, 2026). "These mutations also need to be investigated given the fact that ITGB1 and ITGB7 are cancer-associated genes and are FDA-approved drug targets." (PMID 40362482, 2025). "Our analysis revealed associations between the expression of COL1A1, ITGB1, THY1, and PDGFRA genes and different cancer stages in UCEC, however, the results were insignificant due to the lesser number of samples." (PMID 40817072, 2025). "The flow cytometry analysis showed that knockdown of ITGA4 or ITGB1 can inhibit the effect of recombinant SPP1 protein or cancer cells on the function of CD8+T cells (Additional file3N)." (PMID 40665335, 2025). "Crucially, Piezo1/ITGB1 overexpression promoted cancer development by suppressing apoptosis and enhancing proliferation." (PMID 40667648, 2025). "Yet, overexpression of TIMP1 by various cancer types has been associated with increased disease severity and pro-metastatic effects, partly mediated by TIMP1/CD63/ITGB1 activation of focal adhesion kinase (FAK) signaling." (PMID 40265926, 2025). "Immune-related genes, such as COL1A1, ITGB1, THY1, and PDGFRA, have been implicated in various cancers, but their roles in UCEC remain underexplored." (PMID 40817072, 2025). "IGF2BP1 can also affect the stability of ITGB1 mRNA through m6A modification to promote its translation and facilitate cancer cell metastasis and drug resistance." (PMID 41280724, 2025). "Cumulatively, these data support the phosphorylation-sensitive changes of Illusia and that active dephosphorylation of ITGB1 is dynamically balanced with kinase-mediated phosphorylation in cancer and normal cells." (PMID 40419795, 2025). "This visualization highlights key genes (TIMP3, BRAF, and ITGB1, among the top 10 genes) that participate in multiple cancer-related and metabolic pathways, suggesting potential functional hubs and crosstalk among signaling networks." (PMID 41294900, 2025). "Here, we show that dynamic ITGB1 phosphorylation facilitates the recruitment of a proinvasive Dok1 complex to support invadopodia formation, cancer invasion and metastatic dissemination." (PMID 40419795, 2025). "In cancer zone A, Col1a2-Itga9/Itgb1 and Fn1-Cd44 interactions among cancer cells, along with Angptl4-Sdc2 signaling between CAFs 1 and cancer cells, collectively activated stromal remodeling and promoted EMT." (PMID 40723284, 2025). "The flow cytometry analysis showed that knockdown of ITGA4 or ITGB1 can inhibit the effect of recombinant SPP1 protein or cancer cells on M2 TAM polarization (Additional file4N)." (PMID 40665335, 2025). "ITGB1 is a well-established mediator of extracellular matrix adhesion, migration, and invasion across cancer types, including TNBC." (PMID 41301480, 2025). "Collectively, these data suggest that ITGB1 is a crucial membrane receptor that mediates cancer stemness and drug resistance in HCC cells via the PI3K/AKT/β-catenin signaling cascade." (PMID 41392988, 2025). "ITGB1 was found to be overexpressed in cancers such as gastric and breast cancer, correlating with poorer clinical outcomes." (PMID 41392988, 2025). "The results showed that CAFs and ITGB1 expression were positively correlated in 18 cancer types (P < 0.05 in all four algorithms)." (PMID 38402311, 2024). "Following this, we focused our study on how ITGB1 expression affects IGF-1R activity in migratory cancer cells." (PMID 39608716, 2024). "Our pan-cancer analysis of ITGB1 gives evidence in favor of a further investigation into its oncogenic function in various cancer types." (PMID 38402311, 2024).
cancer (continued). "We also used IHC data from the "Human Protein Atlas" database to look at the ITGB1 protein levels in various cancer types." (PMID 38402311, 2024). "There were strong connections via the GAS6-AXL/MERTK and THBS1-CD36/CD47/ITGA4/ITGB1/LRP1 axes between cancer cells (contributing ligands) and TAMs (contributing receptors)." (PMID 38169544, 2024). "ITGB1 is known to have tumorigenic effects, and inhibition of ITGB1 inhibits cancer cell proliferation." (PMID 38732562, 2024). "When we analyzed expression of these receptors in our scRNA-seq dataset, the Ptprc expression was the highest in CD8 T cells, while Itgb1 was predominantly expressed in cancer cells and NK cells." (PMID 38169569, 2024). "This review summarizes the biological roles of ITGB1 in benign diseases and cancers, and compiles the current status of ITGB1 function and therapy in various aspects of tumorigenesis and progression." (PMID 38279122, 2024). "Overall, these data show that ITGB1 is involved in nearly every stage of cancer progression, from the formation of primary tumors to metastasis." (PMID 38279122, 2024). "In migratory cancer cells, which express high levels of ITGB1, suppression of ITGB1 increased IGF-1R stability and its retention on the plasma membrane during cell adhesion." (PMID 39608716, 2024). "The abnormal activation of ITGB1 promotes downstream signaling, enhancing the tolerance of cancer cells to radiation." (PMID 38279122, 2024). "We used the STRING online resource to conduct protein–protein interaction network analysis (PPI) in order to further investigate the probable molecular mechanism of ITGB1 in the emergence of cancer." (PMID 38402311, 2024). "When an appropriate unit or ligand interacts with ITGB1, it triggers important molecules that give cancer cells the ability to adhere and metastasize, and to undergo EMT." (PMID 39258668, 2024). "In LC, ITGB1-actin-MT1-MMPs/cofilin/F-actin signaling axis promotes cancer cell motility in an acidic microenvironment." (PMID 38279122, 2024). "The overall frequency of genetic alterations in ITGB1 was found to be relatively low in pan-cancer studies." (PMID 38402311, 2024). "Integrinβ1 (ITGB1) is an extracellular matrix receptor that is often involved in angiogenesis, cell cycle regulation, and cancer invasion." (PMID 38582791, 2024). "The development of vasculogenic mimicry (VM) by cancer cells is one program, and ITGB1 is a crucial regulator thereof." (PMID 38279122, 2024). "To investigate the mRNA expression profile of ITGB1 in pan-carcinoma, we performed differential analyses using the "Gene DE" module of TIMER 2.0 and the "Single Gene Analysis" module of GEPIA." (PMID 38402311, 2024). "Another finding supporting the increase in ITGB1 in our system is that VIM is important for ITGB1 trafficking to the leading edge of migrating carcinoma cells, which have completed the process of cell transformation." (PMID 39682709, 2024). "(c) Images show the effect of modulating matrix adhesion via Crispr KO of ITGB1 in cancer cells (green) in both organotypic and spheroid assays including fibroblasts (magenta)." (PMID 36892272, 2023). "On the other hand, integrin-α5β1 (ITGA5/ITGB1) on cancer cells bind fibronectin assembled on the surface of fibroblasts." (PMID 36936987, 2023). "Curcumin decreases circ-PRKCA, a sponge for miR-384, resulting in miR-384 increase and ITGB1 decrease, which, all together, leads to a decrease of the biological aggressiveness of cancer cells." (PMID 37376060, 2023). "Over-expression of ITGB1 in ccRCC strikingly reduced Mcl-1 expression, indicating that ITGB1 promotes cancer progression by modulating Mcl-1." (PMID 36969848, 2023).